SPON1 (spondin 1)
Diseases named in the same sentence as SPON1 in open-access papers (continued):
Sharing a sentence is not in itself a finding about the gene and the disease.
gastric cancer (2 papers, 2021 to 2023). A primary or metastatic malignant neoplasm involving the stomach. "SPON1 that encodes a secreted extracellular matrix glycoprotein is one of the DEGs in metastatic or poorly differentiated gastric cancer, being associated with tumor aggressiveness and poor prognosis of patients." (PMID 34900998, 2021). "These analyses suggested that TNXB and SPON1 may play important roles in tumor infiltrating immune cells, particularly macrophages, in gastric cancer." (PMID 36520032, 2023). "Interestingly, Spondin‐1 (SPON1) and Tenascin‐X (TNXB), two proteins that have not been associated with gastric cancer before, showed significant upregulation, consistent with our proteomic findings." (PMID 36520032, 2023).
neuroblastoma (2 papers, 2022 to 2024). Neuroblastoma (NB) is the most common solid, extracranial childhood tumor. "In addition, SPON1 was shown to promote survival in a murine neuroblastoma model under stressful conditions via a p38 MAPK dependent pathway, ultimately upregulating IL‐6 expression." (PMID 35487760, 2022).
Obesity (2 papers, 2018 to 2025). Accumulation of substantial excess body fat. "Among these, SPON1 encodes an extracellular matrix protein previously associated with body mass index and obesity in murine models." (PMID 40662169, 2025). "Then we validated 7 obesity or lipid metabolism related genes (Hif1a, Spon1, H19, Adrb2, Vldlr, Zfp36, Smad3), and found that compared to CTL group, Vldlr was hypermethylated and low expressed, and Hif1α was demethylated and high expressed in the VDD group." (PMID 29321608, 2018).
Bladder Urothelial Carcinoma (1 paper, 2022). "SPON1 was found to be downregulated in DLBC and upregulated in Bladder Urothelial Carcinoma." (PMID 36354023, 2022).
Burkitt lymphoma (1 paper, 2022). A rare form of malignant mature B-cell non-Hodgkin lymphoma. "Analysing gene expression data of Burkitt lymphoma transcriptome sequencing from African patients revealed six biomarkers (ADAMTSL4, SEMA5B, ADAMTS15, THBS2, SPON1 and THBS1) as possible indicators for diagnostic and prognostic targets towards BL management." (PMID 36354023, 2022).
cutaneous melanoma (1 paper, 2019). A primary melanoma arising from atypical melanocytes in the skin. "The selected candidate proteins in this study have been recently assessed in UM (i.e. OPN, MIA, CEACAM-1, MIC-1, and HSP27) and/or cutaneous melanoma as well as other cancers (i.e. SPON1 and POSTN) by either ELISA or immunohistochemistry or other techniques." (PMID 30867659, 2019).
diabetic nephropathy (1 paper, 2014). "We found that Spon1 expression is significantly higher in the kidneys of subjects with diabetic nephropathy." (PMID 24667548, 2014). "Immunostaining of human biopsy samples demonstrated that protein expression of Spon1 was also markedly increased in kidneys of patients with both early and late HIVAN and diabetic nephropathy." (PMID 24667548, 2014). "When we queried the renal expression of Spon1 in human diabetic nephropathy deposited in a web-based database called Nephromine, we found that the mRNA level of Spon1 was significantly higher in kidneys from individuals with diabetic nephropathy compared to non-diabetic controls." (PMID 24667548, 2014).
hair-loss (1 paper, 2019). "For disease-gene mapping, we found the role of these genes in alopecia and hair-loss and observed that SPON1 is the enriched term." (PMID 30993080, 2019).
hepatoblastoma (1 paper, 2016). Hepatoblastoma (HB) is a malignant hepatic tumor and is the most common pediatric liver cancer. "The mRNA expression levels of CYP2B6, SPON1, and GSG1L in human hepatoblastoma (HepG2) cells were measured after 24 h of exposure to CAR agonists." (PMID 27010727, 2016).
Lewis Lung Carcinoma (1 paper, 2024). "To determine if SPON1 can be secreted from IMs, we cocultured BM derived IMs from WT or Spon1–/– mice with Lewis Lung Carcinoma (LLC) cells." (PMID 38716730, 2024).
lung carcinoma (1 paper, 2024). "Consistent with SPON1 promoting lung cancer progression, LUSC tumors expressing high levels of SPON1 had decreased overall survival." (PMID 38716730, 2024). "To test the direct effects of SPON1 on lung cancer promotion and collagen production, we treated several NSCLC lines with recombinant SPON1 in vitro." (PMID 38716730, 2024). "This suggests that lung cancer CAFs also have a collagen gene response through SPON1/LRP8 signaling, but cancer cells are also capable of “mimicking” CAFs by using the SPON1/LRP8 axis to produce collagen." (PMID 38716730, 2024). "SPON1+ TIMs are sufficient to promote lung cancer metastases." (PMID 38716730, 2024). "We confirmed that the lung cancer cells (LN2E1, LN4K1, and LLC) had low expression of Spon1 compared with IMs isolated from BM or TIMs isolated from LLC tumors." (PMID 38716730, 2024).
lymph node metastasis (1 paper, 2023). "We discovered overexpression of TNXB and SPON1 in patients with lymph node metastasis, which correlates with poor survival of GAC patients." (PMID 36520032, 2023). "Our study found for the first time that TNXB and SPON1 are highly expressed in the primary tumor tissues of GAC patients with lymph node metastasis, and that overexpression of TNXB and SPON1 is associated with poor prognosis of GAC patients." (PMID 36520032, 2023).
metastatic disease (1 paper, 2024). "CD8 T cell depletion resulted in increased metastatic disease in both WT and Spon1–/– mice." (PMID 38716730, 2024).
neuritis (1 paper, 2020). A neuropathy arising from inflammation of one or more nerves. "For example, Spondin-1 is a cell adhesion protein usually attached to the sensory neuron cells and outgrowth of neuritis that encode a secreted basement membrane molecule similar in function to F-spondin of vertebrate." (PMID 32164277, 2020).
pancreatic cancer (1 paper, 2023). "For instance, it has been reported that SPON1 accelerates malignant behaviors in pancreatic cancer cells, such as cell proliferation, colony formation, and chemoresistance." (PMID 37179355, 2023).
pancreatic ductal adenocarcinoma (1 paper, 2022). An infiltrating adenocarcinoma that arises from the epithelial cells of the pancreas. "This study investigated the specific molecular mechanism and the roles of extracellular matrix protein Spondin 1 (SPON1) in the development of pancreatic ductal adenocarcinoma (PDAC)." (PMID 35487760, 2022).
pulmonary fibrosis (1 paper, 2023). Chronic progressive interstitial lung disorder characterized by the replacement of the lung tissue by connective tissue, leading to progressive dyspnea, respiratory failure, or right heart failure. "To investigate the expression and role of SPON1 in pulmonary fibrosis, we analyzed SPON1 expression in BLM-induced mouse lung tissue." (PMID 37416778, 2023). "Therefore, we speculated that FOXO3 may affect the expression and function of SPON1 circRNA in pulmonary fibrosis." (PMID 37416778, 2023). "FOXO3 directly bound to SPON1 and its promoter, promoted the formation of SPON1 circRNA, inhibited the nuclear translocation of Smad3 through interaction with Smad3 and sponge Smad7 as the targeted miRNAs to promote Smad7 expression, and ultimately inhibited the progression of pulmonary fibrosis." (PMID 37416778, 2023). "Although SPON1 activates the TGF-β signaling pathway, the role of SPON1 and its circ-RNA in pulmonary fibrosis remains unclear." (PMID 37416778, 2023). "Although circSPON1 was found to mediate the effect of FOXO3 on pulmonary fibrosis in this study, the specific regulatory mechanism of FOXO3 in the alternative splicing of SPON1 pre-mRNA remains unclear." (PMID 37416778, 2023).
serous carcinoma (1 paper, 2024). "Those tumors with HRD were all diagnosed as high grade serous carcinoma, specifically harboring fusions involving NRG1 and the JAG1, SPON1, and TNFRSF12A partner genes." (PMID 39575425, 2024).
serous ovarian cancer (1 paper, 2023). "The reason is unknown, but it is reasonable because STIC, a precursor legion for high-grade serous ovarian cancer, moderately expressed SPON1." (PMID 37179355, 2023). "The frequency of high SPON1 expression in high-grade serous ovarian cancer was higher than that in non-high-grade serous ovarian cancer, although the difference was not significant (P = 0.058)." (PMID 37179355, 2023).
type 2 diabetes (1 paper, 2021). "We observed decreased methylation at this CpGs, which was associated with the increased risk of CVD, and a previous study for DNA methylation in adipose tissue also showed SPON1 in corresponding to the site cg23284931 was negatively correlated with type 2 diabetes." (PMID 33980183, 2021).
cancer (18 papers, 2013 to 2025). A tumor composed of atypical neoplastic, often pleomorphic cells that invade other tissues. "While these SPON1+ TIMs were about 5 times more abundant in the stroma (PanCK–) as compared with cancer cell islets (PanCK+), the SPON1+ TIMs in the cancer cell islets were associated with collagen deposition in the tumor." (PMID 38716730, 2024). "Some of these genes are reported in other cancer-implicated signaling pathways such as Ras (SPON1), SHH (SMO), and Notch (HEY2)." (PMID 39620202, 2024). "SPON1 gene expression was most significantly and positively connected with cancer-associated fibroblasts (CAFs) among tumor-infiltrating stromal and immune cells." (PMID 37179355, 2023). "For example, Tff3, Hpse, Slit1, Spon1, Spock1, and Spock3 are associated with increased cancer cell invasion and were upregulated in Rreb1-/-, and Selenbp1 and Serpin6b are tumor suppressor genes that were downregulated." (PMID 33929320, 2021). "Additionally, we found that Spon1 loss in the host, or Lrp8 loss in cancer cells, resulted in a significant decrease of both high-density collagen matrices and metastases." (PMID 38716730, 2024). "Also, the density of SPON1+ TIMs was modestly correlated with LRP8+ and pSMAD2+ cancer cells (r = 0.27, P < 0.0001), further suggesting an association between SPON1+ TIMs in the tumor and LRP8-associated TGF-β1 activation in cancer cells." (PMID 38716730, 2024). "Furthermore, although fibrillar collagens are typically thought to arise from cancer-associated fibroblasts (CAFs), we observed substantial intrinsic upregulation of many collagen genes in cancer cells in response to recombinant SPON1 treatment." (PMID 38716730, 2024). "Building upon these previous findings, we identified a mechanistic link by which SPON1+ TIMs signal through LRP8+ cancer cells to activate TGF-β1, resulting in robust cancer cell production of fibrillar collagens." (PMID 38716730, 2024). "Inflammatory monocyte SPON1 acts on LRP8-expressing cancer cells to activate TGF&beta;, which in-turn triggers cancer cell mediated collagen remodeling to promote NSCLC metastases." (PMID 38716730, 2024). "Together, these findings support that SPON1 mediates its effects on cancer metastasis and collagen production through its cognate receptor, LRP8." (PMID 38716730, 2024). "We further explored the mRNA expression of TNXB and SPON1 in other types of cancer from TCGA, similarly comparing the differences in primary tumor samples from patients with or without LNM." (PMID 36520032, 2023). "SPON1 is an extracellular matrix protein that is involved in neural cell adhesion and outgrowth, although its pathological role in cancers remains to be understood." (PMID 35054873, 2022). "SPON1 mRNA expression was upregulated in cancer tissues compared with the corresponding adjacent pancreatic tissues." (PMID 35487760, 2022). "In our tumor validation set we focused on AKAP12, DCBLD2, NT5E with a higher stringent threshold cut-off, and SPON1 whose expression appears to be highly cancer-related in the explorative “training series”." (PMID 24133572, 2013). "To evaluate how SPON1 may have a role in promoting cancer progression, we further selected the top 11 genes from this initial list with the highest hazard ratios, with a score above 1 indicating worse survival in patients with LUSC." (PMID 38716730, 2024). "This suggests that juxtacrine interactions of SPON1+ TIMs with cancer cells may be sufficient to promote collagen production." (PMID 38716730, 2024). "Interestingly, we also found that levels of LRP8 expression on CAFs were comparable with those of our cancer cell lines, and their ability to respond to SPON1 to produce collagens was also comparable." (PMID 38716730, 2024). "To evaluate whether SPON1 secreted from IMs could have a similar effect as recombinant SPON1, we isolated BM IMs from either WT C57BL/6 or Spon1–/– mice and cocultured them with cancer cell spheroids for 3 consecutive days." (PMID 38716730, 2024).
cancer (continued). "Furthermore, we found that TNXB and SPON1, two ECM proteins, are associated with LNM in GAC patients and play important roles in cancer cell migration." (PMID 36520032, 2023). "Using TCGA, we first examined the expression of SPON1 gene in various types of cancer." (PMID 37179355, 2023). "SPON1 is a cell adhesion molecule that promotes neurite extension and expresses at high levels in the floor plate, and has been shown to upregulate in other cancer types." (PMID 36520032, 2023). "Recently, we have demonstrated that F-spondin, encoded by SPON1, participates in the signaling pathway by which 2ME exerts its apoptotic activity in cancer cells so that this 2ME-target gene is a good marker for the biological effects of this estrogen metabolite." (PMID 37446151, 2023). "Although several studies have reported the dysregulation of SPON1 and its role in promoting tumour growth, the specific mechanism by which SPON1 affects cancer development remains largely unknown." (PMID 35487760, 2022). "Collectively, our findings provide not only new insights into the role of SPON1 in cancer progression but also a novel and effective therapeutic approach for the eradication of PDAC, which remains a life‐threatening disease without an effective, targeted therapeutic strategy." (PMID 35487760, 2022). "Additionally, the dataset from the GTEx revealed that SPON1 transcripts were very weakly detected in a variety of normal adult organs of humans, which had expression levels that were extremely lower than those in cancer tissues." (PMID 37179355, 2023). "Core genes with a higher DC (> 8), EC (> 0.06), LAC (> 2.0), BC(> 200), and NC(> 0.3) in the enriched modules were also expressed differentially in TCGA‐CHOL data (36 tumor samples and 9 adjacent cancer samples), including FGF2, IGF1, CAV1, SPON1, and ADAMTS4." (PMID 40304434, 2025). "As supported by our TMA analyses, SPON1 TIM expression is coordinated with dual LRP8+ and pSMAD2+ cancer cell expression, which is also correlated with collagen deposition and poor prognosis." (PMID 38716730, 2024). "However, it is largely unknown how SPON1 contributes to advancing cancer progression." (PMID 37179355, 2023). "Here, by integrating bioinformatic approaches with in vitro and in vivo modeling of the TME, we demonstrate that F-Spondin–expressing (SPON1-expressing) TIMs promote fibrillar collagen production and metastases through a LRP8/TGF-β1 signaling axis in cancer cells." (PMID 38716730, 2024). "While these data support an emerging role of SPON1 in cancer progression, all studies thus far have focused on cancer-derived SPON1 and have not considered the role of SPON1 from the TME." (PMID 38716730, 2024). "Some of these genes such as Vascular Endothelial Growth Factor (VEGF), Vascular Endothelial Growth Factor Receptor 1 (VEGFR1), Spondin 1 (Spon1), Transforming Growth Factor beta (TGFβ) or Metalloproteinase 9 (MMP9) were exclusively upregulated in cancer cells from the peritoneal cavity." (PMID 35844581, 2022).
tumor (13 papers, 2009 to 2026). "Furthermore, either loss of Spon1 in TIMs or genetic deletion of Lrp8 expression on tumor cells was sufficient to significantly abrogate NSCLC metastases and collagen content within the TME." (PMID 38716730, 2024). "Furthermore, changes in the transcriptional expression of C-Man-Trp metabolism-related genes, C-mannosyltransferases (Dpy19l1 and Dpy19l3), and thrombospondin type I repeat superfamily genes (Thbs1, Spon1, and cellular communication network factor 1) were noted in tumor-associated cells and tissues." (PMID 41812877, 2026). "In contrast, factors like ATL3 (Log2 ratio 1.40), ERGIC1 (Log2 ratio 1.64), SPON1 (Log2 ratio 1.25), TNFAIP8 (Log2 ratio 1.99), and VDAC1 (Log2 ratio 1.20), associated with a “highly favorable” prognosis, suggest roles in tumor suppression." (PMID 39858632, 2025). "Using IVIS imaging, before adoptive transfer, we observed significantly decreased tumor burden in all Spon1–/– mice groups compared with WT mice." (PMID 38716730, 2024). "Compared with non–tumor-bearing mice, we observed that IMs isolated from tumors and circulating IMs in tumor-bearing mice showed overexpression of Spon1." (PMID 38716730, 2024). "Consistent with our mouse model, the Mono1 population in blood and tumor samples of patients with NSCLC showed elevated SPON1 expression." (PMID 38716730, 2024). "We also evaluated SPON1 levels in the serum and observed a significant increase in tumor-bearing mice." (PMID 38716730, 2024). "To seek experimental evidence, we applied western blot analysis and confirmed higher expression of TNXB and SPON1 in GAC tumor tissues from patients with LNM." (PMID 36520032, 2023). "Together, we confirmed that TNXB and SPON1 were upregulated in GAC tumor tissues from patients with LNM, thus substantiated our proteomic data." (PMID 36520032, 2023). "To gain an insight into the nature of SPON1-expressing stromal cells, we subsequently evaluated correlation between the expression of SPON1 gene and the profile of tumor-infiltrating immune cells by the EPIC and MCP-counter methods of the TIMER 2.0 database." (PMID 37179355, 2023). "AKAP12, DCBLD2, NT5E and SPON1 are particularly represented in the signatures and selected for validation in vivo on two independent patients cohorts comprising 140 tumor tissues and 60 matched normal tissues." (PMID 24133572, 2013). "However, s.c. tumor growth of LLC tumors grew significantly faster in Spon1–/– mice compared with WT." (PMID 38716730, 2024). "SPON1 is highly expressed in tumor-infiltrating inflammatory monocytes." (PMID 38716730, 2024). "Thus, while CAFs’ roles in collagen production are well established, this work reveals a previously unappreciated role of how SPON1+ TIMs can induce collagen deposition within the ECM via tumor cells." (PMID 38716730, 2024). "Thus, it appears that TNXB and SPON1 displayed certain degree of correlation with the tumor immune microenvironment." (PMID 36520032, 2023). "SPON1 was more diffusely upregulated in grade II tumor and infiltrating multiple stromal cell types, while LAMA4 was enriched in tumor ECs in grade III samples." (PMID 41366031, 2025). "Using the WT or Lrp8-KO LLC model in WT and Spon1–/– mice, we found significantly decreased tumor burden by IVIS in WT mice with Lrp8-KO tumors, and a significantly diseased metastatic burden in the when both SPON1 and LRP8 are knocked out." (PMID 38716730, 2024). "In a separate validation experiment, we confirmed that Il-1β, Spon1, and Cfb showed significantly increased expression in TIMs in the LN2E1 model when compared with IMs from the BM of non–tumor-bearing mice." (PMID 38716730, 2024). "Furthermore, SPON1 and TNFAIP8 have demonstrated context-dependent effects, with implications in both tumor promotion and inhibition." (PMID 39858632, 2025).